BRCA2 (BRCA2 DNA repair associated)
Diseases named in the same sentence as BRCA2 in open-access papers (continued):
Sharing a sentence is not in itself a finding about the gene and the disease.
lung carcinoma (105 papers, 2004 to 2026). "Among the six novel BRCA2‐associated cancers found in our study, the statistical evidence was notably strong for lung cancer and mesothelioma (p < 1E‐10), but moderate for oral, liver, small intestine, and laryngeal cancers." (PMID 40462315, 2025). "Approximately 0.79% of primary lung cancer patients harbor BRCA2 mutations, with this prevalence decreasing to 0.5% in advanced NSCLC cases." (PMID 40584122, 2025). "Due to our inability to identify a lung cancer cell line exhibiting tolerance to the loss of BRCA2, we sought to incorporate both hATM (−/−) and hBRCA2 (−/−) isogenic cell lines into our studies." (PMID 38807759, 2024). "Carriers of BRCA1 and BRCA2 P/LP variants accounted for 0.79% and 0.60% of 1017 lung cancer patients with adenocarcinoma or squamous cell carcinoma, respectively, in the TCGA cohort." (PMID 37930190, 2023). "Among 29 cancer disposition genes with germline mutations detected in Chinese cohort and/or TCGA lung cancer cohort, Only 11 from 29 genes are identified in both cohorts and BRCA2 mutations are significantly more common in Chinese cohort (p = 0.015)." (PMID 35273153, 2022). "Mutations in BRCA2 gene were associated with shorter survival in breast, colorectal and bladder cancers, but longer survival in ovarian, endometrial and lung cancers." (PMID 35444210, 2022). "In this study, BRCA2 K3326X was more significantly associated with lung cancer of the squamous variety than lung adenocarcinoma (OR = 2.47, p = 4.74 × 10−20 and OR = 1.47, p = 4.66 × 10−4, respectively)." (PMID 33503928, 2021). "The authors found BRCA2 K3326X to be significantly associated with lung cancer (OR = 2.47, p = 4.74 × 10−20)." (PMID 33503928, 2021). "Variants in both BRCA1 and BRCA2 were present across all histologies of lung cancer and controls, with a prevalence of 20.0% (12/37) and 6.3% (1/16) for BRCA1, and 18.3% (11/37) and 18.8% (3/16) for BRCA2 in lung cancer patients and controls, respectively." (PMID 34217228, 2021). "We observed that lung cancer was more common in families of BRCA2 c.9976A>T carrier probands (0.22) when compared to BRCA1/2 wild type (0.13) or pathogenic BRCA1 (0.09) or BRCA2 (0.09) variant carrier families." (PMID 33672545, 2021). "Lung cancer was more prevalent in families carrying the c.9976A>T variant compared to pathogenic BRCA1 or BRCA2 carrier families." (PMID 33672545, 2021). "Materials and Methods: We systematically reviewed cohort studies to explore the association of BRCA 1 and BRCA2 with various cancers except lung cancer." (PMID 34577828, 2021). "In line with this, based on associations between this BRCA2 variant and upper aero-digestive tract and lung cancer risk, PARP1 inhibitors were suggested as potential treatment strategies." (PMID 33672545, 2021). "Both patients with a BRCA2 germline variant had additional cancers, one lung cancer, the other one chronic lymphatic leukemia/small cell lymphocytic lymphoma." (PMID 32354124, 2020). "Materials and Methods: Observation studies were systematically reviewed to explore the association of BRCA1 or BRCA2 with lung cancer." (PMID 32349445, 2020). "When analyzing palindrome-altering GWAS variants with low allele counts (AC < 100) in 1000G (which represents a healthy population), we found one SNP (rs11571833) that is associated with both breast and lung cancers in the BRCA2 gene (with AC = 22)." (PMID 33298903, 2020). "Here, hsa_circ_0046264 and BRCA2 shared common target miRNA, miR-1245, and up-regulation of miR-1245 in lung cancer resulted from the low expression of hsa_circ_0046264 caused the down-regulation of BRCA2." (PMID 29891014, 2018). "We also found that the PTV rs11571833 in BRCA2 was associated with lung cancer (MAF = 0.934%, p = 7.3 × 10−11, OR = 1.19, 95% CI: 1.13–1.25)." (PMID 29691392, 2018).
lung carcinoma (continued). "There were also two individuals with lung cancer, one of whom (II:7) is known to carry the BRCA2 mutation on the basis of the reconstructed haplotype and the presence of this mutation in his children." (PMID 14735197, 2004). "This study further indicates that pathogenic BRCA2 mutations could serve as a biomarker for predicting the efficacy of PARP inhibitors in lung cancer patients." (PMID 40182045, 2025). "Our results support the notion that PARP inhibitors administered in combination with immunotherapy using EGFR/Notch bsAbs have broad potential for the treatment of various tumours beyond hereditary BRCA1-deficient and BRCA2-deficient tumours, including lung cancer." (PMID 37441599, 2023). "Similarly, pathogenic germline variants in BRCA1 and BRCA2 were detected in 6 (0.34%) and 16 (0.79%) participants, respectively, in another study which involved 1764 Chinese lung cancer patients." (PMID 37930190, 2023). "As for BRCA2 pathogenic variants, three of them were in exposed patients, and only one in an unexposed patient, c.2806_2809delAAAC (p.A938fs), which was already detected in breast, ovary, and lung cancer patients by another study." (PMID 35875117, 2022). "The most commonly mutated gene in this Chinese lung cancer cohort was BRCA2 in 14 patients." (PMID 35273153, 2022). "Interestingly, we discovered one case (P11) out of the 313 HRR germline-mutant lung cancers harboring a reversion mutation BRCA2 c.2978G>C p.W993S." (PMID 35281878, 2022). "However, lung cancer was more prevalent in families carrying c.9976A>T compared to pathogenic BRCA1/BRCA2 carrier families." (PMID 33672545, 2021). "Ultrasound imaging highlighted tumor development on the left lung surface, and proteomic analysis identified specific biomarkers associated with lung cancer, such as ADAMTS12, BRAF, BRCA2, and TIF1α." (PMID 40584122, 2025). "BRCA2 has also been demonstrated to exhibit increased mRNA levels and poor prognosis in lung cancer." (PMID 39267750, 2024). "Gene-based burden test showed that 9.52% and 6.78% of individuals with breast and lung cancer had predicted loss of function variants in BRCA1 and BRCA2, respectively." (PMID 37461096, 2023). "We found that 1.17% of 1117 unselected Chinese lung cancer patients carried BRCA1 (0.54%) and BRCA2 (0.63%) P/LP variants." (PMID 37930190, 2023). "CDK1 and CDK12 inhibition led to HR deficiency by decreasing HR repair proteins RAD51, BRCA1, and BRCA2 in lung cancer." (PMID 37370140, 2023). "With a prediction error of 0.74 and a CVC of 6.60, the optimal interaction model between the environmental variable and the investigated genes, XRCC1_28152 and BRCA2, was found for lung cancer." (PMID 38137497, 2023). "Hu et al11 demonstrated that there were 64 (1.03%) carriers of BRCA1 and BRCA2 pathogenic germline variants in 6220 Chinese non‐small cell lung cancer (NSCLC) patients, with BRCA2 variants being the most predominant." (PMID 37930190, 2023).
lung carcinoma (continued). "In this study, we also investigated the correlations between 35 polymorphisms in 9 DNA repair genes (XRCC3, BRCA2/ZAR1L, XPC, RAD52, MAD2L2, NFKB1, NFKBIA, TNFRSF1A, and FASN) with platinum-based chemotherapy prognosis in 399 patients with lung cancer." (PMID 35899106, 2022). "Specifically, we identified three lung cancer patients with EML4-ALK, who each also harbored an activating mutation in KRAS, and loss of function mutations in BRCA2 and PTEN, respectively." (PMID 36369474, 2022). "Of note, his daughter, carrying the same BRCA2 mutation, was diagnosed with TNBC when she was 41, and his family history included also one case of gastric cancer, one lung cancer and one brain cancer." (PMID 34034685, 2021). "A genome-wide association study of 159 cases and 2707 controls including the genotyping of 1476 non-synonymous SNPs in 871 candidate genes found increased prevalence of BRCA2 K3326X in lung cancer of unspecified type (OR = 1.72, 95% CI 1.15–2.57, p = 0.0075)." (PMID 33503928, 2021). "For example, somatic BRCA2 and ATM mutations were correlated with HRD in bladder cancer, lung cancer, and colon cancer." (PMID 34572800, 2021). "To this end, we employed the established H1299 lung cancer model allowing for DOX-inducible shRNA-mediated depletion of BRCA1 or BRCA2." (PMID 32085572, 2020). "Lung cancer organoids respond to drugs based on their genomic alterations: a BRCA2-mutant organoid to olaparib, an EGFR-mutant organoid to erlotinib, and an EGFR-mutant/MET-amplified organoid to crizotinib." (PMID 31488816, 2019). "HMMR forms a complex with BRCA1 or BRCA2 together with other proteins, and high expression of HMMR was associated with poor survival in liver, pancreatic and lung cancer." (PMID 30785874, 2019). "Hsa_circ_0046264 inhibited lung cancer development through acting as a ceRNA which regulated miR-1245 and indirectly activated BRCA2." (PMID 29891014, 2018). "Hsa_circ_0046264 and BRCA2 were down-regulated in lung cancer tissues while miR-1245 was up-regulated." (PMID 29891014, 2018). "In this study, we found BRCA2 was down-regulated in lung cancer tissues and supposed that it was a suppressive gene." (PMID 29891014, 2018). "Hsa_circ_0046264 induced apoptosis but inhibited proliferation and invasion of lung cancer cells through targeting miR-1245 to up-regulate BRCA2." (PMID 29891014, 2018). "Hsa_circ_0046264 and BRCA2 were lowly expressed in lung cancer tissues while miR-1245 was high expressed." (PMID 29891014, 2018). "The results showed that EG22 induced significantly higher levels of DNA damage than TMZ in a Chinese Hamster lung cancer BRCA2-mutant VC8 and proficient tumour cells V79 cells." (PMID 28800752, 2017). "Recently, an imputation study identified two rare variants rs11571833 in BRCA2 and rs17879961 in CHEK2 were associated with lung cancer." (PMID 27632928, 2016). "Previous studies have shown that two rare variants, rs11571833 in BRCA2 and rs17879961 in CHEK2 were associated with lung cancer." (PMID 27632928, 2016). "To prove the finding that the synthetic lethal interactions were also existed in lung cancer, we have tested the autoantibodies to PARP1and BRCA1/BRCA2 in sera from lung cancer patients." (PMID 25865228, 2015). "This high prevalence of autoantibody to PARP1 (22.4%) was notable, and meanwhile there was very low frequency of autoantibodies to BRCA1 (4.3%) and to BRCA2 (1.1%) in lung cancer sera." (PMID 25865228, 2015). "Antisense-mediated reduction of IDO, alone and (in a synthetic lethal approach) in combination with antisense to the DNA repair protein BRCA2 sensitizes human lung cancer cells to olaparib and cisplatin." (PMID 24784564, 2014). "Recently studies have shown a possible association between lung cancer and BRCA1 and BRCA2 mutation." (PMID 16721370, 2006).
lung carcinoma (continued). "Two patients had non-recurrent BRCA2 mutations: one carrier had colorectal cancer and synchronous BC and OC, and the other had early-onset synchronous BC and lung carcinoma." (PMID 39684352, 2024). "Compared to the controls, enrichment of BRCA1 variants in lung cancer patients was statistically significant, with an OR of 4.193 (95% CI 1.382–10.768, p = 0.006), but it was not significant for BRCA2." (PMID 37930190, 2023). "Besides, five P/LP variants (one in ATM, two in BRCA2, and two in PALB2) were also found in 1117 lung cancer patients." (PMID 37930190, 2023). "In fact, when their prevalence in the controls was taken into account, P/LP variants of BRCA1 but not BRCA2 were significantly related with an elevated risk of lung cancer, as demonstrated by our study." (PMID 37930190, 2023). "circ_0046264 suppresses the malignancy of lung carcinoma cell by acting on the miR-1245/BRCA2 axis." (PMID 36593867, 2022). "Hsa_circ_0046264 could up-regulate BRCA2 by targeting miR-1245 to induce apoptosis and inhibit cell proliferation and invasion in lung cancer cells." (PMID 34079579, 2021). "Our group previously performed a meta-analysis and found no increase in lung cancer incidence due to BRCA1 or BRCA2 gene mutation." (PMID 34577828, 2021). "Our meta-analysis showed that individuals who are BRCA1 or BRCA2 carriers do not have an increased risk of lung cancer." (PMID 32349445, 2020). "Male BRCA-associated tumors were predominantly stage II or III disease with a higher frequency of BRCA2 mutations and were more commonly found in cutaneous melanoma and carcinoma of the lung, bladder, and stomach compared to those in non-BRCAm carriers." (PMID 33054725, 2020). "Furthermore, genetic variants in the HR genes BRCA2 and RAD52 have been liked to lung cancer susceptibility." (PMID 33203852, 2020). "BRCA2 mRNA downregulation was confirmed by qPCR to ensure that lack of sensitization was not due to inadequate transfection, and the level of BRCA2 mRNA knockdown was similar to that observed in A549 lung cancer cells (which are sensitized to olabarib by BRCA2 ASO treatment)." (PMID 26959114, 2016). "In addition, we identified a nonsense mutation (3326K>X) in the BRCA2 gene in the germline of a patient (MM08) with a family history of cervical (mother) and lung cancer (sister)." (PMID 25233892, 2014). "For example, germline variants in BRCA2 and ATM may cause increased risk for lung cancer and sarcoma, two tumor types in our study that revealed a significant number of tumor (and germline) variants in hereditary cancer risk genes not typically associated with these tumor types." (PMID 36261688, 2023). "BRCA2 ASO treatment sensitized all three lung cancer cell lines to olaparib across the entire range of drug concentrations regardless of mutational signature and load, suggesting that BRCA2 inhibition may render lung tumors with disparate backgrounds sensitive to PARP inhibition." (PMID 26959114, 2016). "While aerodigestive tract cancers are believed to be a rare part of the neoplastic spectrum of BRCA2, no other high penetrance lung-cancer-predisposition gene has been identified, and until recently, lung cancer has been attributed almost entirely to environmental exposure, chiefly tobacco." (PMID 22384118, 2012). "POLQ, BRCA2, ATM, ATR, PARP4, and POLD1 alterations were most commonly observed in the entire advanced lung cancer cohort." (PMID 34604048, 2021).
lung carcinoma (continued). "Therefore, miR-1245 and its target gene BRCA2 might affect the progression of lung cancers." (PMID 29891014, 2018). "In lung cancer sera, 22.4% (21/94) was shown to have autoantibody to PARP1, 4.3% (4/94) was shown to BRCA1, 1.1% (1/94) was shown to BRCA2, 4.3% (4/94) was shown to PARP1 and BRCA1, and 0% (0/94) was shown to PARP1 and BRCA2." (PMID 25865228, 2015). "While lung cancer is not typically related to germline BRCA1/2 mutations, there have been a few instances: there are somatic in the BRCA1 or BRCA2 gene in approximately 5-10% of non-small cell lung cancer cases." (PMID 36249053, 2022). "Only works that included a direct gene test cohort study and were selected for our meta-analysis revealed that lung cancer incidence was not increased in BRCA1 or BRCA2 carriers." (PMID 32349445, 2020). "Besides, activating BRCA2 by MIR-1245 suppressed the proliferation and invasion of lung cancer cells." (PMID 33162799, 2020). "This study showed that families with BRCA1 or BRCA2 have no increased risks for lung cancer on the basis of current available studies." (PMID 32349445, 2020). "However, seven BRCA1 and six BRCA2 germline truncations (MAF≤0.05%) were detected in other cancer types (three each in endometrial, stomach and lung cancers, two in kidney cancer and one each in prostate and head and neck cancers)." (PMID 26689913, 2015). "Indeed, in BRCA1- or ATM-mutated breast, ovarian and lung cancer lines, low EME1 levels associated with decreased Olaparib sensitivity, which was not the case in BRCA2-mutated or unaltered cells." (PMID 39994444, 2025). "However, this did not imply that BRCA2 played a more important role in Chinese lung cancer patients than BRCA1." (PMID 37930190, 2023). "Two patients (P003 and P006) who met Amsterdam criteria, whose families suffered from colorectal cancer, lung cancer and bladder cancer, were not identified as MMR mutation carriers, but they carried many other tumor-associated genes, such as BRCA2, CDH1, MET, ATM, NF1." (PMID 35372080, 2022). "The reason for this difference might be that there was no synthetic lethal interactions between PARP1 and BRCA1/BRCA2 in lung cancer or there might be existed other types of synthetic lethal interactions, which is supported by recent studies." (PMID 25865228, 2015). "The protein expression of hMLH1, hMSH2, XRCC1, XRCC3, XRCC5, BRCA1, and BRCA2 repair genes in B[a]P-treated HPV-positive and -negative lung cancer cells was analyzed by western blotting." (PMID 26918347, 2016).